RNF144A (ring finger protein 144A)
Description:
E3 ubiquitin-protein ligase which accepts ubiquitin from E2 ubiquitin-conjugating enzymes UBE2L3 and UBE2L6 in the form of a thioester and then directly transfers the ubiquitin to targeted substrates. Mediates the ubiquitination and degradation of the DNA damage kinase PRKDC during DNA damage. Positively regulates DNA virus or exogenous cytosolic DNA-triggered innate immune response by mediating STING1 ubiquitination and increasing its 'Lys-6'-linked ubiquitination and translocation from the endoplasmic reticulum to the Golgi leading to downstream signaling pathways. Plays a positive role in EGF-dependent cell proliferation by prolonging EGF/EGFR signaling during EGF stimulation through EGFR ubiquitination. Increases ERK activity independently of EGFR signaling by promoting polyubiquitination and subsequent degradation of VRK3 in the cytosol.
Synonyms: KIAA0161; RNF144; UBCE7IP4; hUIP4; UIP4
Tractability: Antibody: UniProt places it where antibodies can reach, with high confidence; UniProt predicts a signal peptide or a membrane-spanning region; its Gene Ontology location is reachable by antibodies, with medium confidence. PROTAC: UniProt records ubiquitination sites on it; ubiquitination databases record sites on it.
Gene: Protein-coding gene on chromosome 2 (6,917,386 to 7,068,286, forward strand). Ensembl gene ENSG00000151692.
Subcellular location: Cell membrane; Cytoplasmic vesicle membrane; Endosome membrane; Endoplasmic reticulum membrane
Subcellular location (Human Protein Atlas): Vesicles
Pathways (Reactome):
Metabolism of proteins: E3 ubiquitin ligases ubiquitinate target proteins
Gene Ontology:
Molecular function: protein binding; ubiquitin protein ligase activity; ubiquitin conjugating enzyme binding; ubiquitin-protein transferase activity; zinc ion binding
Biological process: pattern recognition receptor signaling pathway; protein K6-linked ubiquitination; protein ubiquitination
Cellular component: cytoplasmic vesicle membrane; endoplasmic reticulum membrane; endosome membrane; Golgi apparatus; plasma membrane; ubiquitin ligase complex; cytoplasm
Genetic constraint (gnomAD): Loss-of-function variants: 11 observed, 33.09 expected, observed/expected ratio (o/e) 0.33, 90% interval 0.21 to 0.55. The upper end of that interval is the gene's LOEUF score, 0.55, which puts it in group 2 of 6, group 1 being the genes least tolerant of losing a copy. Missense variants: 314 observed, 373.99 expected, observed/expected ratio (o/e) 0.84, 90% interval 0.76 to 0.92. Synonymous variants: 145 observed, 145.61 expected, observed/expected ratio (o/e) 1, 90% interval 0.87 to 1.14.
Homologues: Orthologues: chimpanzee RNF144A (99% identical), macaque RNF144A (99% identical), mouse Rnf144a (97% identical), dog RNF144A (96% identical), pig RNF144A (96% identical), rat Rnf144a (96% identical), rabbit RNF144A (96% identical), guinea pig RNF144A (95% identical), tropical clawed frog rnf144a (89% identical), zebrafish rnf144aa (86% identical), Caenorhabditis elegans C17H11.6 (29% identical), Caenorhabditis elegans Y49F6B.9 (24% identical). Paralogues in human: RNF144B (55% identical), RNF19A (30% identical), RNF19B (30% identical), ANKIB1 (26% identical), ARIH1 (23% identical), ARIH2 (21% identical), RNF14 (21% identical), RNF217 (21% identical), PRKN (17% identical).
Diseases named in the same sentence as RNF144A in open-access papers:
RNF144A is named in the same sentence as 28 diseases in open-access papers, as found by Europe PMC text mining. Sharing a sentence is not in itself a finding about the gene and the disease. The quoted sentences say what the papers report.
breast carcinoma (17 papers, 2016 to 2025). "Reduced levels of RNF144A have been associated with PD-L1 stabilization and tumorigenesis in mouse bladder cancer models and poor prognosis in patients with breast cancer." (PMID 40723216, 2025). "Second, pyrosequencing and qPCR analysis showed that the methylation levels of RNF144A promoter are negatively associated with its mRNA expression levels in breast cancer cells." (PMID 29473320, 2018). "Studies have also implicated CPNE8, MAGED1, and RNF144A in ovarian and breast cancers." (PMID 32849822, 2020). "In addition, the expression levels of RNF144A in breast cancer cells are associated with breast cancer cellular sensitivity to PARP inhibitor olaparib." (PMID 29212245, 2017). "Moreover, we found that the expression levels of RNF144A in breast cancer cells are associated with cellular sensitivity to PARP inhibitor olaparib." (PMID 29212245, 2017). "RNF144A promotes ubiquitination degradation of YY1, inhibits tumor cell proliferation and migration, and promotes ubiquitination degradation of HSPA2, and these mechanisms lead to the inhibition of breast cancer by RNF144A." (PMID 40756570, 2025). "There is a CpG island in the RNF144A promoter, and knockdown of the endogenous methyl CpG island-binding structural domain 4 (MBD4) of RNF144A in breast cancer upregulated the expression of RNF144A." (PMID 40756570, 2025). "On the other hand, the knockdown of RNF144A promoted the malignant phenotype of breast cancer cells." (PMID 40756570, 2025). "Regarding cancer, RNF144A has been connected to several cancer kinds, including colorectal, stomach, and breast cancers." (PMID 38313020, 2024). "Through ubiquitin ligase activity-dependent modulation of HSPA2′s stability and carcinogenic properties, RNF144A suppresses tumors in breast cancer." (PMID 38313020, 2024). "RNF144A governed PARP inhibitor sensitivity via targeting PARP1 in ubiquitin-dependent manner in breast cancer cells." (PMID 37215134, 2023). "Our previous studies showed that RNF144A is epigenetically silenced in breast cancer cells by promoter hypermethylation and its expression levels are associated with favorable prognosis of breast cancer patients." (PMID 35103856, 2022). "We further demonstrated that RNF144A suppresses breast cancer cell growth, migration, and invasion through, at least in part, negatively regulating GMFG expression." (PMID 35103856, 2022). "In this study, we provide new mechanistic insights into tumor suppressor function of RNF144A in breast cancer cells." (PMID 35103856, 2022). "Collectively, these results suggest that RNF144A suppresses breast cancer cell proliferation, migration, and invasion through, at least in part, regulating GMFG expression." (PMID 35103856, 2022). "RNF144A was downregulated in a subset of primary breast tumors and restoration of RNF144A suppressed breast cancer cell proliferation, colony formation, migration, invasion in vitro, tumor growth, and lung metastasis in vivo." (PMID 34943954, 2021). "There is a marginal correlation between the expression levels of MBD4 and RNF144A in all of patients with breast cancer (n = 1093, p = 0.0738)." (PMID 29473320, 2018). "In the present study, we provide evidence for the first time that promoter hypermethylation is involved in transcriptional repression of RNF144A in breast cancer cells." (PMID 29473320, 2018). "Evidence from pharmacological and genetic modulation of MBD4 demonstrated that MBD4 is involved in RNF144A expression in breast cancer cells." (PMID 29473320, 2018). "Consistently, knockdown of endogenous RNF144A in human breast cancer MDA-MB-231 cells by specific short hairpin RNAs (shRNAs) targeting human RNF144A (shRNF144A) decreased the ubiquitination levels of endogenous PARP1 (compare lane 3 with 2)." (PMID 29212245, 2017). "In addition, RNF144A expression was decreased due to promoter hypermethylation in breast cancer cells." (PMID 37215134, 2023).
breast carcinoma (continued). "Epigenetic depletion of RNF144A has been detected in numerous human cancers, including glioblastoma, breast cancer, and bladder cancer, indicating that RNF144A may act as a tumor suppressor." (PMID 37497216, 2023). "Moreover, RNF144A targeted the stability of HSPA2 via ubiquitin-dependent regulation in breast cancer." (PMID 37215134, 2023). "In conclusion, the findings presented in this study suggest that RNF144A exerts tumor suppressor functions in breast cancer cells through targeting transcription factor YY1 for proteasomal degradation, thus blocking YY1-mediated transcriptional activation of GMFG expression in breast cancer cells." (PMID 35103856, 2022). "Functional rescue assays showed that ectopic expression of RNF144A suppressed the proliferative, migratory, and invasive potential of breast cancer cells, and the noted effects were partially restored by re-expression of GMFG in RNF144A-overexpressing breast cancer cells." (PMID 35103856, 2022). "In contrast, knockdown of RNF144A promoted malignant phenotypes of breast cancer cells." (PMID 34943954, 2021). "Moreover, RNF144A-mediated suppression of breast cancer cell proliferation, migration, and invasion was rescued by ectopic HSPA2 expression." (PMID 34943954, 2021). "Given that the majority of CpG islands in the human genome are heavily methylated 30, these results indicate that RNF144A promoter might be methylated in breast cancer." (PMID 29473320, 2018). "Our recent studies demonstrated that induced expression of RNF144A decreases the sensitivity of breast cancer cells to poly(ADP‐ribose) polymerase (PARP) inhibitor olaparib through targeting DNA repair protein PARP1 for ubiquitination and subsequent proteasomal degradation." (PMID 29473320, 2018). "Following these observations, we next examined whether there is a negative correlation between the expression levels of MBD4 and RNF144A in breast cancer in The Cancer Genome Atlas (TCGA) database." (PMID 29473320, 2018). "Consistently, RNF144A promoter methylation levels are associated with its transcriptional silencing in breast cancer cells, and treatment with DNA methylation inhibitor 5‐Aza‐2‐deoxycytidine (AZA) reactivates RNF144A expression in cells with RNF144A promoter hypermethylation." (PMID 29473320, 2018). "To directly analyze whether expression of RNF144A is regulated by promoter methylation, we next examined the effects of DNA methylation inhibitor AZA on the reactivation of RNF144A in breast cancer cells by qPCR and immunoblotting analyses." (PMID 29473320, 2018). "Furthermore, stable expression of Flag-RNF144A in human breast cancer MCF-7, MDA-MB-231, and SK-BR-3 cells resulted in a decrease in the protein levels of endogenous PARP1." (PMID 29212245, 2017). "Our recent studies demonstrated that RNF144A is downregulated in breast cancer (manuscript in preparation), which may provide a molecular basis of why PARP1 is upregulated in breast cancer at the protein level." (PMID 29212245, 2017). "We next examined whether MBD4 is involved in the regulation of RNF144A in breast cancer cells." (PMID 29473320, 2018). "RNF144A targets YY1 for proteasomal degradation to decrease the production of GMFG, hence acting as a tumor suppressor in breast cancer." (PMID 38313020, 2024). "Collectively, these findings reveal that RNF144A negatively regulates GMFG expression by targeting YY1 for proteasomal degradation, thus inhibiting the proliferation, migration, and invasion of breast cancer cells." (PMID 35103856, 2022). "To gain mechanistic insights into the biological functions of RNF144A in breast cancer progression, we established MDA-MB-231 cell lines stably expressing empty vector pCDH and Flag-RNF144A by lentiviral infection." (PMID 35103856, 2022).
breast carcinoma (continued). "Eventually, functional rescue assays demonstrated that the inhibitory effects of RNF144A on breast cancer cell proliferation, migration, and invasion was reversed by re-expression of GMFG in RNF144A-overexpressing cells." (PMID 35103856, 2022). "In this study, we found that YY1 transcriptionally activates GMFG expression, and RNF144A interacts with YY1 and promotes its degradation through the ubiquitin–proteasome pathway, thus blocking YY1-mediated induction of GMFG expression in breast cancer cells." (PMID 35103856, 2022). "They found that RING finger protein 144A (RNF144A), a member of the RING-in-between-RING family of E3 ubiquitin ligases, functions as a tumor suppressor in breast cancer and target HSPA2 for degradation." (PMID 34943954, 2021). "Clinically, low RNF144A and high HSPA2 expression in breast cancer patients was correlated with aggressive clinico–pathological characteristics and decreased overall and disease-free survival." (PMID 34943954, 2021). "Third, treatment of breast cancer cells with DNA methylation inhibitor AZA effectively restored the mRNA and protein expression of endogenous RNF144A." (PMID 29473320, 2018). "In summary, findings presented here show that reduced RNF144A expression in breast cancer cells is regulated by promoter hypermethylation and MBD4 in breast cancer cells." (PMID 29473320, 2018). "However, the regulatory mechanism of RNF144A in breast cancer remains unknown." (PMID 29473320, 2018). "It was found that RNF144A interacts with the heat-shock protein family A member 2 (HSPA2), an oncoprotein, and promotes its ubiquitination degradation, thus negatively regulating breast cancer." (PMID 40756570, 2025). "Furthermore, RNF144A degraded YY1 and inhibited the expression of GMFG as well as suppressed oncogenesis in breast cancer." (PMID 37215134, 2023). "RNF144A exerts a negative regulatory effect on the expression of GMFG in breast cancer by specifically targeting YY1-degrading proteasomes, thereby preventing the proliferation, migration, and invasion of breast cancer cells." (PMID 38259686, 2023). "To address whether RNF144A acts as a tumor suppressor in breast cancer through regulating GMFG expression, we re-expressed GMFG in MDA-MB-231 and Hs578T cells stably expressing RNF144A." (PMID 35103856, 2022). "CCK8 and colony formation assays revealed that ectopic expression of RNF144A in MDA-MB-231 and Hs578T cells suppressed breast cancer cell proliferation and colony formation, but the noted effects were partially rescued following re-expression of GMFG in RNF144A overexpressing cells." (PMID 35103856, 2022). "Notably, the ligase activity-defective mutants of RNF144A impaired its ability to induce ubiquitination and degradation of HSPA2, and to suppress breast cancer malignant phenotype as compared with its wild-type counterpart." (PMID 34943954, 2021). "Interestingly, we found that the alteration frequency for RNF144A gene mutation and copy number deletion in human breast cancer is no more than 0.2% and 0.4%, respectively, suggesting that those two types of genetic alterations may not be the major cause of RNF144A deregulation in breast cancer." (PMID 29473320, 2018). "To confirm these results, we next analyzed the methylation levels in the CpG islands of RNF144A in 30 pairs of breast cancer specimens and matched adjacent noncancerous breast tissues by pyrosequencing." (PMID 29473320, 2018). "We next analyzed the DNA methylation levels of RNF144A promoter at the R1 and R2 regions by pyrosequencing in normal mammary epithelial cell line HBL100 and 5 representative breast cancer cell lines, including MCF7, T47D (luminal‐type), MDA‐MB‐453 (HER2‐positive), BT20, and MDA‐MB‐231 (TNBC)." (PMID 29473320, 2018).
breast carcinoma (continued). "Together, these findings define RNF144A as a novel regulator of PARP1 protein abundance and a potential determinant of PARP inhibitor sensitivity in breast cancer cells, which may eventually guide the optimal use of PARP inhibitors in the clinic." (PMID 29212245, 2017). "Moreover, induced expression of RNF144A decreases PARP1 protein levels and renders breast cancer cells resistant to the clinical-grade PARP inhibitor olaparib." (PMID 29212245, 2017). "Importantly, we found that endogenous RNF144A interacted with endogenous PARP1 in human breast epithelial HBL100 cells and human breast cancer BT474 cells by IP analysis using an anti-PARP1 antibody." (PMID 29212245, 2017). "In addition, the effects of shRNA-mediated knockdown of endogenous RNF144A on the protein and mRNA levels of PARP1 were also observed in human breast cancer MCF-7 cells (respectively)." (PMID 29212245, 2017). "RNF144A and Parkinson protein 2 (PARK2, also known as Parkin) are members of the RBR E3 ligase family that have been identified as tumor suppressor genes in breast cancer, their low expression levels in breast cancer may be attributed to hypermethylation in their promoter." (PMID 35216622, 2022). "In contrast, induced expression of RNF144A did not significantly affect the protein levels of BRCA1, another key DNA repair protein in breast cancer cells." (PMID 29212245, 2017).
bladder cancer (4 papers, 2023 to 2025). "Mice with RNF144A deficiency were more prone to initiation of bladder cancer after carcinogen exposure." (PMID 37215134, 2023). "RNF144A depletion in mice caused a decrease of tumor infiltration CD8+ T-cells in the carcinogen-induced bladder cancer." (PMID 37215134, 2023). "The interaction between RNF144A and PD-L1 highlights the therapeutic significance of targeting RNF144A in cancer treatment, particularly in bladder cancer, where PD-L1 plays a crucial role in immune evasion." (PMID 38474186, 2024). "In a recent study, the basal-squamous subtype of bladder cancer has been found to express relatively low levels of RNF144A and high levels of immune checkpoint protein programmed cell death ligand-1(PD-L1)." (PMID 37497216, 2023). "The basal-squamous subtype of bladder cancer expresses relatively low levels of RNF144A and high levels of immune checkpoint protein programmed cell death ligand-1 (PD-L1)." (PMID 37497216, 2023). "In bladder cancer cells, depletion of RNF144A elevated the stabilization of PD-L1 protein and enhanced carcinogen-mediated bladder oncogenesis." (PMID 37215134, 2023). "Hence, depletion of RNF144A increased the expression of PD-L1, DNA-PKcs and BMI1, resulting in the carcinogen-mediated the development of bladder cancer." (PMID 37215134, 2023).
ovarian carcinoma (3 papers, 2024 to 2025). A malignant neoplasm originating from the surface ovarian epithelium. "RNF144A inhibits the growth of tumors and the characteristics of ovarian cancer stem cells by controlling the degradation of LIN28B via the ubiquitin-proteasome pathway." (PMID 38313020, 2024).
breast tumors (2 papers, 2018 to 2021). "Clearly, further studies are warranted to confirm the relationship between DNA methylation and RNF144A expression levels in a large size of breast tumor samples." (PMID 29473320, 2018). "Results showed that the relative methylation levels of RNF144A promoter at the regions R1 and R2 were significantly higher in breast tumor samples relative to matched normal breast tissues." (PMID 29473320, 2018). "Here, we report that RNF144A promoter contains a putative CpG island and the methylation levels of RNF144A promoter are higher in primary breast tumors than those in normal breast tissues." (PMID 29473320, 2018). "First, RNF144A promoter contains a putative CpG island, and the methylation levels of RNF144A promoter are higher in primary breast tumors than those in normal breast tissues." (PMID 29473320, 2018). "Indeed, we found significantly higher methylation levels of RNF144A promoter in primary breast tumors relative to normal breast tissues." (PMID 29473320, 2018).
schizophrenia (1 paper, 2025). A major psychotic disorder characterized by abnormalities in the perception or expression of reality. "A genome-wide association study (GWAS) conducted in a cohort of 738 schizophrenia patients receiving standard antipsychotic therapy identified RNF144A as a pharmacogenomic susceptibility locus associated with metabolic adverse effects." (PMID 40756570, 2025). "Specific mechanisms by which RNF144A regulates schizophrenia are to be further explored." (PMID 40756570, 2025).
uterine cancer (1 paper, 2019). Primary or metastatic malignant neoplasm involving the uterine corpus and/or the cervix. "As revealed by an inspection of the cBioPortal database, many types of cancers, such as lung, prostate, breast, and uterine cancer, have amplifications or mutations in RNF144A." (PMID 30658672, 2019).